CPEB2 (cytoplasmic polyadenylation element binding protein 2)
Description:
May play a role in translational regulation of stored mRNAs in transcriptionally inactive haploid spermatids. Binds to poly(U) RNA oligomers (By similarity). Required for cell cycle progression, specifically for the transition from metaphase to anaphase.
Synonyms: CPE-BP2; hCPEB-2; CPEB-2
Tractability: PROTAC: ubiquitination databases record sites on it; its protein half-life has been measured.
Gene: Protein-coding gene on chromosome 4 (15,002,481 to 15,070,153, forward strand). Ensembl gene ENSG00000137449.
Subcellular location: Cytoplasm
Subcellular location (Human Protein Atlas): Cytosol
Gene Ontology:
Molecular function: RNA binding; GTPase inhibitor activity; mRNA 3'-UTR AU-rich region binding; mRNA 3'-UTR binding; mRNA regulatory element binding translation repressor activity; ribosomal large subunit binding; ribosomal small subunit binding; ribosome binding; translation factor activity, RNA binding; nucleic acid binding; translation regulator activity
Biological process: cellular response to hypoxia; cellular response to insulin stimulus; negative regulation of cytoplasmic translation; negative regulation of cytoplasmic translational elongation; regulation of translation; translation
Cellular component: cytoplasm; nucleus; neuron projection; synapse
Genetic constraint (gnomAD): Loss-of-function variants: 45 observed, 43.45 expected, observed/expected ratio (o/e) 1.04, 90% interval 0.81 to 1.33. The synonymous counts are far from expectation, so gnomAD's model fits this gene poorly and the ratio says little. Missense variants: 1,255 observed, 927.88 expected, observed/expected ratio (o/e) 1.35, 90% interval 1.29 to 1.42. Synonymous variants: 613 observed, 399.9 expected, observed/expected ratio (o/e) 1.53, 90% interval 1.43 to 1.64.
Homologues: Orthologues: chimpanzee CPEB2 (99% identical), macaque CPEB2 (98% identical), pig CPEB2 (96% identical), dog CPEB2 (95% identical), rat Cpeb2 (92% identical), mouse Cpeb2 (91% identical), rabbit CPEB2 (63% identical), tropical clawed frog cpeb2 (57% identical), guinea pig CPEB2 (53% identical), zebrafish cpeb2 (36% identical), Drosophila melanogaster orb2 (28% identical), Caenorhabditis elegans cpb-1 (17% identical), and 1 more. Paralogues in human: CPEB3 (40% identical), CPEB4 (40% identical), CPEB1 (17% identical).
Diseases named in the same sentence as CPEB2 in open-access papers:
CPEB2 is named in the same sentence as 28 diseases in open-access papers, as found by Europe PMC text mining. Sharing a sentence is not in itself a finding about the gene and the disease. The quoted sentences say what the papers report.
breast carcinoma (8 papers, 2019 to 2023). "Splice variant isoforms of cytoplasmic polyadenylation element-binding protein 2 (CPEB2) function differently in breast cancer." (PMID 33435156, 2021). "Recently, it was identified that CPEB2 is a tumor suppressor gene, further validating miR526b and miR655 as oncogenic miRNAs promoting breast cancer by collectively targeting this gene." (PMID 32707933, 2020). "SiRNA-mediated CPEB2 knockdown in MCF7 breast cancer cells also resulted in enhanced oncogenic properties tested in vitro." (PMID 31185986, 2019). "Recently, a common target of both miRNAs CPEB2 has been validated as a tumor suppressor gene in breast cancer." (PMID 31277414, 2019). "The roles of CPEB2 in breast cancer appear to be complex, depending on the expression of different CPEB2 isoforms." (PMID 31185986, 2019). "The roles of CPEB2 in breast cancer depend on the expression of different CPEB2 isoforms." (PMID 38158431, 2023). "In addition, CPEB2 has been shown to act as a tumor suppressor gene in breast cancer." (PMID 33344235, 2020). "CPEB2 is one of the top six genes, together with ESR1, with the strongest correlation with ER+ breast cancer prognosis." (PMID 33670895, 2021). "We also knocked down CPEB2 in the poorly malignant, CPEB2A dominant breast cancer cell line MCF7, using a pool of siRNAs." (PMID 31185986, 2019). "Human breast cancer tissues (n = 105) revealed a lower mRNA expression for CPEB2 isoform A and also a lower A/B isoform ratio than in non-tumour breast tissues (n = 20), suggesting that CPEB2A accounts for the tumor-suppressor functions of CPEB2." (PMID 31185986, 2019). "We examined the expression of CPEB2 isoforms A (indistinguishable from E, by the available probe) and B (indistinguishable from D, by the available probe) in 105 breast cancer and 20 histologically confirmed non-tumour breast tissues." (PMID 31185986, 2019). "Finally an examination of breast cancer and non-tumor breast tissues revealed a lower expression CPEB2 isoform A and higher expression of isoform B in cancerous tissues." (PMID 31185986, 2019). "Finally, CPEB2 expression was compared between human breast cancer and non-tumor breast tissues." (PMID 31185986, 2019).
glioma (6 papers, 2022 to 2025). A benign or malignant brain and spinal cord tumor that arises from glial cells (astrocytes, oligodendrocytes, ependymal cells). "This study highlights a mechanism underlying which CPEB2 inhibits giloma cell growth and provides a potential therapeutic target in patients with glioma." (PMID 38158431, 2023). "Further analysis of TCGA data indicated that CPEB2 was significantly associated with poor prognosis in glioma." (PMID 36064747, 2022). "We conclude that CPEB2 is a novel tumor suppressor gene, inhibiting cancer hallmarks of proliferation while promoting apoptosis in glioma cells." (PMID 38158431, 2023). "In the current study, we first analyzed the expression levels of CPEB2 in glioma patient cohorts and identified CPEB2 to be significantly downregulated." (PMID 38158431, 2023). "Our data in this study showed that CPEB2 also induces G1 cell cycle arrest and inhibits cell proliferation in glioma." (PMID 38158431, 2023). "CPEB2 exerts an anti-tumor effect by increasing p21 mRNA stability and inducing G1 cell cycle arrest in glioma." (PMID 38158431, 2023). "Functional characterization of CPEB2 by overexpression and knockdown revealed that it inhibits glioma cell proliferation and promotes apoptosis." (PMID 38158431, 2023). "When we compared CPEB2 expression level across different subtypes of glioma, we found that it is lower in oligodendroglioma and astrocytoma which are low-grade glial tumors as compared to glioblastoma." (PMID 38158431, 2023). "In this study, the functional characterization of the role and molecular mechanism of CPEB2 in glioma were examined using a series of biological and cellular approaches in vitro and in vivo." (PMID 38158431, 2023). "Collectively, these findings demonstrate that CPEB2 inhibits cell proliferation and promotes apoptosis in glioma." (PMID 38158431, 2023). "Different member of CPEBs seems to play paradoxical roles in glioma, and so far, little was known about the correlation between CPEB2 expression and glioma pathogenesis, and the prognostic significance of CPEB2 in glioma remains unclear." (PMID 38158431, 2023). "To determine whether CPEB2 can regulate cell cycle progression in glioma, we analysed cell-cycle progression using flow cytometry after using serum starvation to synchronize U87 cells." (PMID 38158431, 2023). "We also checked if CPEB2 had any effects on cellular apoptosis in glioma." (PMID 38158431, 2023). "Our results showed that CPEB2 inhibited cell proliferation by upregulation of p21, but the regulation of apoptosis by p21 has been demonstrated in a paradoxical manner, so the specific mechanism of promoting glioma cell apoptosis by CPEB2 needs further discussion." (PMID 38158431, 2023). "Taken together, our findings indicate that CPEB2 could be served as a new anticancer therapeutic target in glioma treatment." (PMID 38158431, 2023). "Moreover, CPEB2 inhibits glioma cell proliferation partially dependent on upregulating p21 and further inducing G1 cell cycle arrest." (PMID 38158431, 2023). "Our work shows CPEB2 is significantly downregulated in various glioma patient cohorts." (PMID 38158431, 2023). "In this study, we first found decreased levels of CPEB2 in glioma, and then we proved that CPEB2 could inhibit glioma cells proliferation through upregulating p21 by specifically overexpressing the canonical isoform Q7Z5Q1-2." (PMID 38158431, 2023). "We further studied its role in glioma cell proliferation by CPEB2 overexpression and knockdown." (PMID 38158431, 2023). "In summary, we confirmed that CPEB2 is down-regulated in various glioma patient cohorts." (PMID 38158431, 2023). "Therefore, we only focused on the function and mechanism of the canonical isoform Q7Z5Q1-2 in this study, and whether different CPEB2 isoforms have contradictory function in glioma remains to be further investigated in the future." (PMID 38158431, 2023). "We further examined whether CPEB2 affect glioma cell apoptosis." (PMID 38158431, 2023).
glioma (continued). "Finally, we proved that CPEB2 upregulated p21 expression through increasing p21 mRNA stability, and the proliferation suppression ability of CPEB2 is partially dependent on upregulating p21 and cell cycle progression in glioma." (PMID 38158431, 2023). "We hypothesized that CPEB2 modulates the cell cycle by regulating p21 in glioma." (PMID 38158431, 2023). "In addition, Flow cytometry analysis of cell apoptosis rates in U87 cells pretreated with Cisplatin showed that CPEB2 could promote glioma cell apoptosis." (PMID 38158431, 2023). "However, the role of CPEB2 in glioma progression is unknown." (PMID 38158431, 2023). "Cytoplasmic polyadenylation element binding protein 2 (CPEB2) m6A methylation regulates BBB permeability via regulating splicing factor SRSF5 stability, which could serve as a target for improving glioma-specific chemotherapeutic effects." (PMID 36896007, 2023).
colorectal cancer (5 papers, 2017 to 2023). A primary or metastatic malignant neoplasm that affects the colon or rectum. "Overexpression of miR-186 promoted colorectal cancer cells more sensitive to MTX by targeting CPEB2 (cytoplasmic polyadenylation element binding protein 2)." (PMID 32195180, 2020). "TUG1 mediates MTX resistance in colorectal cancer via sponging miR-186 that targets CPEB2 increasing its protein levels that play an important role in tumorigenesis and chemoresistance." (PMID 31632922, 2019). "In addition, hsa-miR-885-5p has previously been found up-regulated in liver metastases compared to the primary tumor in colorectal cancer, and a regulation involving its predicted target CPEB2 has been suggested." (PMID 31311505, 2019). "Besides, CPEB2 overexpression also could inhibit the methotrexate sensitivity of colorectal cancer." (PMID 37231521, 2023).
hepatocellular carcinoma (2 papers, 2023 to 2024). A malignant tumor that arises from hepatocytes. "In hepatocellular carcinoma tissues, CPEB2 expression was downregulated and associated with miR-210-3p antagonism." (PMID 37514073, 2023). "However, there are still some limitations to this study, and further experiments in vivo should be performed to explore the role of CPEB2 in the metastasis of hepatocellular carcinoma in an animal model." (PMID 37514073, 2023). "The HIF‐1α/miR‐210‐3p/CPEB2 signaling axis regulated the EMT and metastasis of hepatocellular carcinoma." (PMID 39149855, 2024).
Obesity (2 papers, 2023 to 2024). Accumulation of substantial excess body fat. "In obesity research, the knockout of the CPEB2 gene showed its ability to reduce thermogenesis in brown adipose tissue." (PMID 37886940, 2023).
renal carcinoma (2 papers, 2023). A carcinoma arising from the epithelium of the renal parenchyma or the renal pelvis.
triple-negative breast carcinoma (2 papers, 2019 to 2022). An invasive breast carcinoma which is negative for expression of estrogen receptor (ER), progesterone receptor (PR), and human epidermal growth factor receptor 2 (HER2). "CPEB2 has multiple isoforms (A-F), and paradoxically, a high B/A ratio was reported to impart anoikis-resistance and metastatic phenotype in triple- negative breast cancer cells." (PMID 31185986, 2019).
Anxiety (1 paper, 2024). Intense feelings of nervousness, tension, or panic often arise in response to interpersonal stresses. "The exploratory activity in the open field and the anxiety level in the elevated plus maze were comparable between CPEB2-cKONes mice and their cWT littermates." (PMID 38992696, 2024).
Apnea (1 paper, 2020). Lack of breathing with no movement of the respiratory muscles and no exchange of air in the lungs. "We previously found that loss of CPEB2 in the dorsal motor nucleus of the vagus neurons leads to translational upregulation of choline acetyltransferase, thereby increasing pulmonary acetylcholine level to induce bronchoconstriction-associated apnea in neonatal pups." (PMID 32295602, 2020). "Although enhanced cholinergic transmission-induced bronchoconstriction accounts for some apneic episodes and possible mortality in CPEB2-KO neonates, inhalation of an anti-cholinergic bronchodilator only partially rescued the respiratory apnea in CPEB2-KO pups without improving survival." (PMID 32295602, 2020).
emphysema (1 paper, 2020). "Together, CPEB2 deficiency resulted in reduced and mislocalized MYFs during pulmonary alveologenesis, thereby contributing to abnormal deposition of elastic fibers and emphysema-like dysfunction." (PMID 32295602, 2020). "Consequently, CPEB2-KO mice surviving to adulthood show pulmonary dysfunction with decreased elastance and resistance, similar to other emphysema-like mouse models and human BPD." (PMID 32295602, 2020).
glioblastoma (1 paper, 2023). The most malignant astrocytic tumor (WHO grade IV). "We further revealed that CPEB2 expression is lower in grade II and grade III tumors as compared to grade IV glioblastoma using Grade wise expression analysis in Gene Expression database of Normal and Tumor tissues 2 (GENT2) database." (PMID 38158431, 2023). "We also performed TCGA-GBM (GBM n = 156, nontumor n = 5) patient data analyses and found CPEB2 to be decreased in glioblastoma patients." (PMID 38158431, 2023).
head and neck cancer (1 paper, 2023). A primary or metastatic malignant neoplasm affecting the head and neck. "Our analysis showed that CPEB2 expression was significantly reduced in HCC tissues, and its low expression was associated with a higher recurrence risk and poorer prognosis in patients with head and neck cancer." (PMID 37514073, 2023).
leukemia (1 paper, 2017). A malignant (clonal) hematologic disorder, involving hematopoietic stem cells and characterized by the presence of primitive or atypical myeloid or lymphoid cells in the bone marrow and the blood. "High expression of ARID2, JMJD1C, MBNL1, MEF2C, or RUNX2 alone is associated with at least one indicator of poor prognosis in ALL patients, and CPEB2, MBNL1, RUNX2, and ZEB2 are all specifically overexpressed in MLL-FP leukemias." (PMID 28076791, 2017).
lung carcinoma (1 paper, 2022).
melanoma (1 paper, 2016). A malignant, usually aggressive tumor composed of atypical, neoplastic melanocytes. "Mining solid tumours in the CCLE (N=853), and validating mRNA levels experimentally by qRT-PCR (N=20), we found however CPEB1 and CPEB2 to be well expressed in melanomas, with levels even higher than for the majority of solid tumours analysed." (PMID 27857118, 2016). "As the case of melanomas, melanocytes also expressed CPEB1, CPEB2 and CPEB3, but these proteins appear to be unable to compensate for CPEB4 depletion." (PMID 27857118, 2016). "Indeed, our data revealed that melanomas -as other tumour types- express other CPEB family members (particularly CPEB1 and CPEB2), which could have acted in a compensatory manner in the absence of CPEB4." (PMID 27857118, 2016). "Similarly, there are no reports of the CPEB family members CPEB2, CPEB3 and CPEB4 in melanoma." (PMID 27857118, 2016).
prostate carcinoma (1 paper, 2024). A carcinoma that arises from epithelial cells of the prostate gland. "What’s more, our research demonstrated that specific genes, encompassing RNASEK, CPEB2, ARHGAP22, and BRD1, were enriched in the different cell clusters of prostate cancer tissues through the single-cell RNA sequencing localization analysis." (PMID 39600951, 2024).
pulmonary diseases (1 paper, 2020). "Whether deficient CPEB2-controlled translation contributes to pulmonary diseases requires further clinical investigation." (PMID 32295602, 2020).
respiratory failure (1 paper, 2024). The significant impairment of gas exchange within the lungs resulting in hypoxia, hypercarbia, or both, to the extent that organ tissue perfusion is severely compromised. "Because most CPEB2-knockout (KO) mice die within 3 days after birth due to respiratory failure, the SC-CA1 circuit was only investigated in CPEB2-conditional KO (cKOCamk2) mice whose Cpeb2 was ablated in postsynaptic CA1 but not presynaptic CA3 neurons." (PMID 38992696, 2024).